ASAP2 (ArfGAP with SH3 domain, ankyrin repeat and PH domain 2)
Description:
Activates the small GTPases ARF1, ARF5 and ARF6. Regulates the formation of post-Golgi vesicles and modulates constitutive secretion. Modulates phagocytosis mediated by Fc gamma receptor and ARF6. Modulates PXN recruitment to focal contacts and cell migration.
Synonyms: PAG3; PAP; DDEF2; KIAA0400; SHAG1; CENTB3; AMAP2; Pap-alpha
Tractability: Antibody: its Gene Ontology location is reachable by antibodies, with high confidence; UniProt places it where antibodies can reach, with medium confidence; the Human Protein Atlas places it where antibodies can reach. PROTAC: ubiquitination databases record sites on it; its protein half-life has been measured.
Gene: Protein-coding gene on chromosome 2 (9,206,758 to 9,405,683, forward strand). Ensembl gene ENSG00000151693.
Subcellular location: Cytoplasm; Golgi apparatus, Golgi stack membrane; Cell membrane
Subcellular location (Human Protein Atlas): Cytosol; Plasma membrane
Gene Ontology:
Molecular function: protein binding; GTPase activator activity
Cellular component: cytosol; plasma membrane; cytoplasm; Golgi cisterna membrane
Genetic constraint (gnomAD): Loss-of-function variants: 41 observed, 114.52 expected, observed/expected ratio (o/e) 0.36, 90% interval 0.28 to 0.47. The upper end of that interval is the gene's LOEUF score, 0.47, which puts it in group 2 of 6, group 1 being the genes least tolerant of losing a copy. Missense variants: 955 observed, 1,199.5 expected, observed/expected ratio (o/e) 0.8, 90% interval 0.75 to 0.84. Synonymous variants: 472 observed, 467.91 expected, observed/expected ratio (o/e) 1.01, 90% interval 0.94 to 1.09.
Homologues: Orthologues: chimpanzee ASAP2 (99% identical), macaque ASAP2 (99% identical), dog ASAP2 (96% identical), mouse Asap2 (94% identical), rat Asap2 (94% identical), pig ASAP2 (93% identical), guinea pig ASAP2 (90% identical), rabbit ASAP2 (87% identical), tropical clawed frog asap2 (80% identical), zebrafish asap2a (74% identical). Paralogues in human: ASAP1 (60% identical), ASAP3 (42% identical), ACAP2 (20% identical), ACAP3 (19% identical), ARAP1 (18% identical), ARAP2 (18% identical), ACAP1 (18% identical), ARAP3 (17% identical), AGAP2 (15% identical), AGAP1 (15% identical), AGAP3 (14% identical), AGAP4 (12% identical), and 16 more.
Diseases named in the same sentence as ASAP2 in open-access papers:
ASAP2 is named in the same sentence as 23 diseases in open-access papers, as found by Europe PMC text mining. Sharing a sentence is not in itself a finding about the gene and the disease. The quoted sentences say what the papers report.
pancreatic cancers (3 papers, 2021 to 2025). "Similarly, AHNAK2, ARL4C, ASAP2 were all highly expressed in pancreatic cancers, correlated with KRAS G12D mutation and could predict survival in pancreatic cancers." (PMID 35785187, 2022). "Fujii reported that the novel driver gene ASAP2 is a potential druggable target in pancreatic cancer." (PMID 40564276, 2025). "For example, ASAP2 was identified as the novel driver gene and potential druggable target in pancreatic cancer." (PMID 35785187, 2022). "It has been reported that overexpression of ASAP2 is correlated with worse prognosis in pancreatic cancers." (PMID 34030708, 2021). "AHNAK2, ARL4C, ASAP2, SEMA3C were identified as being highly expressed in both KRAS G12D cell lines and pancreatic cancer patients." (PMID 35785187, 2022).
atherosclerosis (1 paper, 2023). A disease characterized by the build-up of fatty material and calcium deposition in the arterial wall resulting in partial or complete occlusion of the arterial lumen. "Additional GWAS hits in the shared cross-species CAD/atherosclerosis subnetworks were peripheral nodes (e.g. CETP, PLCG2, BASP1, MSR1, ST5, ASAP2)." (PMID 38060277, 2023).
bladder cancer (1 paper, 2022). "However, the potential contribution of frequently altered ASAP2 and PCSK6 in the progression of bladder cancer remains unclear, needing to be further investigated." (PMID 36033441, 2022).
cholangiocarcinoma (1 paper, 2023). A carcinoma that arises from the intrahepatic biliary tree (intrahepatic cholangiocarcinoma) or from the junction, or adjacent to the junction, of the right and left hepatic ducts (hilar cholangiocarcinoma). "Further analysis revealed that ASAP2 also exhibited higher expression levels in other types of malignancies, such as cholangiocarcinoma, head and neck squamous cell carcinoma, and lung squamous cell carcinoma." (PMID 37061723, 2023).
experimental autoimmune encephalomyelitis (1 paper, 2022). An autoimmune demyelinating disease of the central nervous system that is produced experimentally in animals by the injection of homogenized brain or spinal cord in Freund's adjuvant. "In vivo, vitamin D reduced the number of apoptotic cells in experimental autoimmune encephalomyelitis (EAE) and promoted macrophage efferocytosis in peritonitis without changing the mRNA level of ASAP2." (PMID 36432619, 2022).
gastric cancer (1 paper, 2022). A primary or metastatic malignant neoplasm involving the stomach. "Circ_ASAP2 is overexpressed in DDP-resistant gastric cancer tissues and cells, the down-regulation of circ_ASAP2 promote the sensitivity and apoptosis of DDP-resistant gastric cancer cells and inhibite cell proliferation, migration and invasion." (PMID 36465346, 2022).
glioma (1 paper, 2020). A benign or malignant brain and spinal cord tumor that arises from glial cells (astrocytes, oligodendrocytes, ependymal cells). "Very recently, another MGMT gene fusion, ASAP2-MGMT, with similar features to the fusions that we have described here in gliomas, has been identified in a medulloblastoma patient that relapsed after TMZ treatment." (PMID 32753598, 2020).
Hepatitis (1 paper, 2023). Inflammation of the liver. "Similarly, ASAP2 had prognostic value for predicting RFS, PFS, and OS in HCC patients with hepatitis according to TCGA dataset." (PMID 37061723, 2023).
multiple sclerosis (1 paper, 2022). A progressive autoimmune disorder affecting the central nervous system resulting in demyelination. "After analyzing the microarray data of human brain samples (GSE131282), the mRNA level of ASAP2 was found to increase in the lesions of gray matter from multiple sclerosis (MS) patients compared to the normal regions from MS patients or healthy individuals." (PMID 36432619, 2022).
nonalcoholic steatohepatitis (1 paper, 2023). "Moreover, the prognostic significance of ASAP2 should be validated with HCC patients with different etiological backgrounds, such as Hepatits C (HCV) and nonalcoholic steatohepatitis (NASH)." (PMID 37061723, 2023).
osteosarcoma (1 paper, 2022). A usually aggressive malignant bone-forming mesenchymal neoplasm, predominantly affecting adolescents and young adults. "We individually depleted ASAP1, ASAP2, or ASAP3 in U2OS human osteosarcoma cells using SMARTpool siRNAs, replated the cells on fibronectin in serum-free media, stained the cells with fluorescent phalloidin, and examined them using laser scanning confocal microscopy." (PMID 35143843, 2022).
peritonitis (1 paper, 2022). Inflammation of the peritoneum (tissue that lines the abdominal wall and covers most of the organs in the abdomen). "Both EAE and peritonitis models validated the promotive effect of vitamin D on efferocytosis in vivo, while the total mRNA level of ASAP2 remained unchanged." (PMID 36432619, 2022).
uterine cancer (1 paper, 2023). Primary or metastatic malignant neoplasm involving the uterine corpus and/or the cervix. "Intriguingly, high ASAP2 levels could also predict poor prognosis across several types of malignancies, including cervical, lung, pancreatic, and uterine cancers, suggesting that ASAP2 is a common contributor to cancer progression." (PMID 37061723, 2023).
virus infections (1 paper, 2022). "Thus, we could better understand the regulatory mechanism underlying ASAP2 transcription and the function of ASAP2, which may serve as a potential treatment target against inflammatory diseases and virus infections." (PMID 36432619, 2022).
cancer (6 papers, 2018 to 2025). A tumor composed of atypical neoplastic, often pleomorphic cells that invade other tissues. "The locus with segmental gains included several cancer-associated genes, e.g., Asap2 and Adam17, in the DMBA-treated organoid-derived adenocarcinomas." (PMID 34912374, 2021). "The locus with segmental gains included several cancer-associated genes, e.g., Asap2 and Adam17." (PMID 34912374, 2021). "These discoveries strongly suggested that ASAP2 is a crucial driver gene in cancer development." (PMID 37061723, 2023). "Their research indicated that some epigenetic drivers, like regulatory regions of ABCC1 and VEGFA, appeared in pan-cancer, while some epigenetic regulators, like FGF19, ASAP2 and EN1, and the PBX3 motif, are cancer specific." (PMID 40041484, 2025). "Bioinformatics analyses of The Cancer Genome Atlas and STRING datasets were performed to explore ASAP2 downstream signaling." (PMID 37061723, 2023). "Some epigenetic drivers appeared in multiple cancers (for example, regulatory regions of ABCC1 and VEGFA; GATA6 and FOX-family motifs), whereas others were cancer specific (for example, regulatory regions of FGF19, ASAP2 and EN1, and the PBX3 motif)." (PMID 37914932, 2023). "For example, the expression of ASAP2, which has been identified as a biomarker for several types of tumor, is up-regulated in HGLO in 16 cancer types and positively correlated with the resistance to DNA topoisomerases inhibitor Topotecan (r = 0.40) and DNA synthesis inhibitor Gemcitabine (r = 0.34)." (PMID 34030708, 2021). "Moreover, other genes from diverse functional groups appeared in our analysis, such as signal transducers promoting cancer growth (CD53, RAB33A, GNA11, CANX, OCRL, GIPC1, and SOS1), microtubule formation (KIF21B) and cell migration (ASAP2)." (PMID 29535628, 2018).
tumor (6 papers, 2021 to 2024). "However, ASAP2 expression patterns in HCC and the association with tumor recurrence are still unclear, and the underlying mechanism by which ASAP2 can mediate HCC invasion and recurrence is also currently not well understood." (PMID 37061723, 2023). "ASAP2, DNM2 and KIF13B encoding signal transduction proteins play crucial roles in tumor proliferation and invasion." (PMID 38529307, 2024). "ArfGAP With SH3 Domain, Ankyrin Repeat And PH Domain 2 (ASAP2), a member of the conventional ArfGAP family of proteins, reportedly exerts dramatic functions in tumor proliferation and mobility." (PMID 37061723, 2023). "Third, whether a reported ASAP2 inhibitor, niclosamide, exhibits any anti-tumor effects in HCC needs to be investigated." (PMID 37061723, 2023). "Interestingly, most of these genes have been implicated in general mechanisms of tumor biology, such as SERPINF1, reported as an inhibitor of angiogenesis and tumor suppressor, ASAP2, an EGFR pathway activator, or ELN and KRT8 related to the process of EMT." (PMID 34758873, 2021). "Notably, ASAP2 expression gradually increased with progressing tumor stage (P = 0.013)." (PMID 37061723, 2023). "Moreover, interfering with CIN85 expression in ASAP2-knockdown HCC cells could almost restore tumor growth and invasion potentials, validating its role in ASAP2-induced c-MET activation." (PMID 37061723, 2023). "Finally, subcutaneous tumor transplantation experiments were performed, and the results demonstrated that silencing ASAP2 could significantly impair tumor growth in vivo, as evidenced by reduced tumor volumes." (PMID 37061723, 2023).
inflammation (1 paper, 2022). Aberrant reaction of the microcirculation characterized by movement of fluid and leukocytes from the blood into extravascular tissues. "To examine the effect of vitamin D on efferocytosis and alteration of Asap2 expression in inflammatory diseases, we constructed a model for central nervous system (CNS) inflammation EAE and thioglycolate peritonitis." (PMID 36432619, 2022).
ASAP2 also shares sentences with these, for which no sentence is quoted: adenocarcinoma (1 paper); head and neck squamous cell carcinoma (1); hepatocellular carcinoma (1); lung squamous cell carcinoma (1); medulloblastoma (1); neuroendocrine carcinoma (1).